PUS1 (pseudouridine synthase 1)
Diseases named in the same sentence as PUS1 in open-access papers (continued):
Sharing a sentence is not in itself a finding about the gene and the disease.
renal carcinoma (2 papers, 2023 to 2026). A carcinoma arising from the epithelium of the renal parenchyma or the renal pelvis. "Considering a vital risk of PUS1 for renal cancer patients, we further developed a clinically predictive model that was workable and may contribute to estimating the prognosis of renal cancer in clinic." (PMID 37315299, 2023). "Consistently, the overall survival of KIRC between high levels of PUS1 and low levels of PUS1 revealed statistical significance, indicating the higher expression of PUS1 may be associated with prognosis of renal cancer." (PMID 37315299, 2023). "As expected, the results exhibited the increase of PUS1 expression in renal cancer." (PMID 37315299, 2023). "According to our findings, the expression of PUS1, PUS7, DKC1 and RPUSD1 is highly expressed in most cancer types, and among those genes, the expression of PUS1, PUS7 and RPUSD1 is markedly upregulated in renal cancers, including KICH, KIRC and KIRP." (PMID 37315299, 2023). "Our results revealed that the expression of PUS1 in 786-O, OSRC2, ACHN cells was higher than other cell lines, and the expression was particularly low in A498 cells, which was consistent with the data of the renal cancer cell line analysis from the CCLE portal." (PMID 37315299, 2023).
triple-negative breast carcinoma (2 papers, 2022 to 2023). An invasive breast carcinoma which is negative for expression of estrogen receptor (ER), progesterone receptor (PR), and human epidermal growth factor receptor 2 (HER2). "In a latest report, PUS1 expression was shown to be positively correlated with triple-negative breast cancer (TNBC) status and tumor grade, and thereby can be potentially applied for predicting poor outcomes and triple-negative status in breast cancer." (PMID 37315299, 2023).
Cirrhosis (1 paper, 2025). A chronic disorder of the liver in which liver tissue becomes scarred and is partially replaced by regenerative nodules and fibrotic tissue resulting in loss of liver function. "We speculate that the detection of combined AFP with PUS1 possible produce an algorithm with better sensitivity for HCC patients with cirrhosis." (PMID 40171259, 2025). "Through subgroup analysis, it was found that expression of PUS1 was abnormally elevated in tumor compared to hepatitis or cirrhosis; it was higher in patients with stage III/IV than in patients with stage I/II, and it was also higher in patients with metastatic tumors than in primary tumors." (PMID 40171259, 2025). "The expression of PUS1 was increased in tumor compared to hepatitis or cirrhosis." (PMID 40171259, 2025).
dyskeratosis congenita (1 paper, 2022). Dyskeratosis congenita (DC) is a rare ectodermal dysplasia that often presents with the classic triad of nail dysplasia, skin pigmentary changes, and oral leukoplakia associated with a high risk of bone marrow failure (BMF) and cancer. "One of the most studied diseases associated with defective pseudouridine modification is dyskeratosis congenita (DC) caused by inactivating mutations in pseudouridine synthase 1 (DKC1)." (PMID 35614935, 2022).
lymph node metastasis (1 paper, 2023). "High expression of PUS1 correlates with larger tumor size, more lymph node metastasis, a worse clinical stage, and poor differentiation." (PMID 37925171, 2023).
metastatic prostate carcinoma (1 paper, 2024). A carcinoma that arises from the prostate gland and has spread to other anatomic sites. "Despite the observed upregulation of PUS1 in metastatic prostate cancer, the mechanisms underlying its upregulation remain unclear." (PMID 39247811, 2024). "Collectively, these results suggest that targeting PUS1 with Mogroside IV-E may represent a promising therapeutic strategy for metastatic prostate cancer, as it not only inhibits tumor cell migration and invasion but also improves survival outcomes in xenograft mice." (PMID 39247811, 2024).
non-small cell lung carcinoma (1 paper, 2026). A group of at least three distinct histological types of lung cancer, including non-small cell squamous cell carcinoma, adenocarcinoma, and large cell carcinoma. "In addition, PUS1 may participate in DNA repair, E2F targeting, MYC targeting, and the G2M checkpoint and promote malignant transformation in non-small cell lung cancer (NSCLC) through mcm5 or XPO1." (PMID 41501031, 2026).
prostatitis (1 paper, 2025). An infectious or non-infectious inflammatory process affecting the prostate gland. "We revealed two Tier 2 genes (NOA1 and ELAC2) and one Tier 3 gene (ACAT1) for BPH, two Tier 3 genes (TRMU and SFXN5) for prostatitis, and six Tier 3 genes (MRPL24, NDUFS6, PUS1, NBR1, GLOD4, and PCBD2) for PCa." (PMID 40919435, 2025). "Our analysis revealed two Tier 2 genes (NOA1 and ELAC2) for BPH, two Tier 3 genes (TRMU and SFXN5) for prostatitis, and six Tier 3 genes (MRPL24, NDUFS6, PUS1, NBR1, GLOD4, and PCBD2) for PCa." (PMID 40919435, 2025).
Sepsis (1 paper, 2023). Sepsis is defined as life-threatening organ dysfunction caused by a dysregulated host response to infection. "Overall, NSUN7, NOP2, PUS1, PUS3, and FTO were identified as important diagnostic markers for sepsis." (PMID 37701433, 2023). "Finally, by using machine learning, we identified five hub RMGs (NSUN7, FTO, NOP2, PUS1, and PUS3), which showed efficient diagnostic value of sepsis." (PMID 37701433, 2023). "Notably, the expression of NOP2 and PUS1 was concurrently increased in patients with sepsis of group C3 in the integrated gene expression matrix, which was consistent with the results observed in our clinic samples." (PMID 37701433, 2023). "For instance, genes mediating RNA Ψ modification (TRUB1, TRUB2, PUS1, RPUSD3, RPUSD4, PUS7, RPUSD2) were mainly suppressed in sepsis." (PMID 37701433, 2023). "To predict the occurrence of sepsis, we constructed a nomogram model for diagnosing sepsis based on the expression levels of five hub RMGs (NSUN7, FTO, NOP2, PUS1 and PUS3)." (PMID 37701433, 2023). "Firstly, we determined the genes expression in PBMCs by qRT-PCR analysis, and found the expression of NSUN7, NOP2, PUS1 and PUS3 in septic patients (septic shock and sepsis) at day 1 were significantly higher than in healthy volunteers, and FTO expression was lower in septic patients." (PMID 37701433, 2023). "In addition, we identified that five RMGs (NSUN7, NOP2, PUS1, PUS3 and FTO) could function as biomarkers for clinic diagnose of sepsis." (PMID 37701433, 2023).
Viral infection (1 paper, 2021). "Viral infection affected host factors that regulate pseudouridine modification, downregulating DKC1 (also called Cbf5), PUS1, PUS3, and RPUSD2 (also called PUS9), as shown in one of six transcriptome experiments, each." (PMID 34502037, 2021).
tumor (14 papers, 2021 to 2026). "Collectively, our findings demonstrate that PUS1 shields tumor cells from endogenous dsRNA accumulation and the consequent detrimental innate immune activation, thereby unveiling a novel and promising therapeutic strategy for RCC." (PMID 42003926, 2026). "PUS1 is involved in several tumor-related processes, such as mitophagy and the PI3K–Akt signaling pathway." (PMID 40260225, 2025). "Six datasets were analyzed and all the results showed that PUS1 expression was increased in tumor tissues." (PMID 40171259, 2025). "In summary, our study revealed that PUS1 is a potential novel tumor biomarker and effective therapeutic target for improving clinical diagnosis, progression surveillance, and prognosis assessment of HCC." (PMID 40171259, 2025). "It was also found that mRNA expression of PUS1 was increased in HCC tumor tissues compared with normal liver tissues in the UALCAN website, E-MTAB-6695, E-MTAB-4171, GSE39791, GSE47197, GSE54236, and GSE25079." (PMID 40171259, 2025). "To further confirm that PUS1 increases EIF3b protein stability, we treated tumor cells with chlorhexidine (CHX), a protein synthesis inhibitor, while knocking down or overexpressing PUS1." (PMID 39247811, 2024). "Collectively, these findings indicate that PUS1 promotes tumor cell bone metastasis both in vivo and in vitro." (PMID 39247811, 2024). "The result has shown that PUS1 expression was higher in airway tissues near the tumor than in those far from the tumor." (PMID 37925171, 2023). "The elements of the model contained tumor grade and PUS1 expression, with the nomogram showing a promising concordance with 1-year, 3-year, and 5-year OS." (PMID 37315299, 2023). "In our study, multi-omics analysis demonstrated a significant increase in PUS1 expression in tumor tissue compared to normal tissue, and high expression of PUS1 was indicative of a poor prognosis in NSCLC." (PMID 37925171, 2023). "In LUSC, PUS1 has significant correlations with tumor purity, B cells, CD8+ T cells, CD4+ T cells, macrophages, neutrophils, and dendritic cells." (PMID 37925171, 2023). "As expected, bioinformatic analysis data revealed that the higher expression levels of PUS1 were correlated with higher tumor grade as well as poor prognosis of patients with RCC." (PMID 37315299, 2023). "Taken together, high expression of PUS1 suppresses the enrichment of antigen-presenting cells, leading to a low response ratio to immunotherapy treatment and increased infiltration of tumor cells." (PMID 37925171, 2023). "Second, the phenotypes of PUS1 knockdown on tumor cells was observed in vitro which need to validated on in vivo experiments in future." (PMID 36457503, 2022). "We found PUS1 knockdown suppressed tumor proliferation and invasion in accordance with our RNA sequencing results." (PMID 36457503, 2022). "Furthermore, depletion of PUS1 in tumor cells significantly sensitizes RCC to immune checkpoint blockade therapy." (PMID 42003926, 2026). "The expression of PUS1 in HCC was positively correlated with tumor stemness." (PMID 40171259, 2025). "We observed a significant increase in PUS1 expression in tumor cell lines." (PMID 39247811, 2024). "Given that PUS1 is one of the 13 pseudouridine modification enzymes, its regulation of tumor cell invasion and migration through its enzymatic reaction remains unknown." (PMID 39247811, 2024). "Integrative analysis of gene expression and mutation data from the TCGA database revealed no significant mutation rate of PUS1 in tumor samples, suggesting that its upregulation is not mutation-driven." (PMID 39247811, 2024). "Knocking down PUS1 resulted in a noticeable decrease in the invasion and migration capabilities of tumor cells, as demonstrated by scratch assays and transwell assays, while proliferation, cell cycle, and apoptosis of tumor cells remained unaffected." (PMID 39247811, 2024).
tumor (continued). "In addition, we analyzed the correlation of PUS1 expression and the airway distance from tumor in NSCLC based on the GSE43580." (PMID 37925171, 2023). "These datasets indicated that PUS1 was significantly up-regulated in tumor tissue." (PMID 37925171, 2023). "Additionally, the ability of tumor cells to invade was remarkably attenuated in low PUS1 expression groups compared with the corresponding control groups." (PMID 36457503, 2022). "Our analysis revealed that PUS1 does not exhibit significant mutations in tumor samples." (PMID 39247811, 2024). "Moreover, decreased stromal and immune cell levels in high PUS1 expression patients demonstrated that tumor cells had a higher proportion in tumor tissues and immune cells infiltration was inhibited, potentially leading to a reduced effectiveness of immunotherapy drugs." (PMID 37925171, 2023). "Additionally, we analyzed the relationship between PUS1 and tumor immune infiltration." (PMID 37925171, 2023). "Besides, we analyzed the relationship between PUS1 and tumor immune infiltration." (PMID 37925171, 2023). "Various PUSs, including PUS7, PUS1, and DKC1, have been shown to regulate tumorigenesis by modulating tumor cell proliferation and apoptosis." (PMID 40260225, 2025). "We found that PUS1, PUS7, and PUS10 maintained consistent copy number amplification in most tumor types." (PMID 39162904, 2024). "Strikingly, patients exhibiting elevated levels of PUS1, PUS3, PUSL1, RPUSD1-4, and TRUB2 demonstrated a significantly shorter disease-free survival, as evidenced by combined analysis with tumor disease-free survival data." (PMID 39247811, 2024). "To further clarify that EIF3b is downstream of PUS1 regulation, we knocked down EIF3b in DU145 and PC-3 cell lines and observed a significant decrease in the migration and invasion abilities of the tumor cells." (PMID 39247811, 2024). "The patients with high expression of PUS1 had lower IPS, which indicated low levels of immunogenicity and conferred tumor evasion from immune responses." (PMID 37925171, 2023). "In order to determine the correlation between PUS1 and development in NSCLC, the relationship between PUS1 and tumor stage or differentiation was analyzed through multiple GEO datasets." (PMID 37925171, 2023). "A high expression of PUS1 correlated with TNBC status and higher tumor grade, as well as poor prognosis of patients with this cancer." (PMID 36457503, 2022). "Increasing evidences have suggested an association between abnormal expression of Ψ synthases (such as PUS1, PUS7, PUS10 and DKC1) and tumor malignant progression." (PMID 35118063, 2021). "The results suggest that PUS family members, including PUS1, RPUSD1, RPUSD3, and PUS7, may contribute to both enhanced tumour stemness and the establishment of an immunosuppressive microenvironment in PAAD." (PMID 41496500, 2026). "Furthermore, individual members such as PUS7 in GBM suppress T‐cell recruitment by reducing chemokine expression, promoting immune evasion, while PUS1 in HCC stabilizes proliferation‐related mRNAs, accelerating tumour growth." (PMID 41496500, 2026). "Therefore, we knocked down PUS1 expression in DU145 and PC-3 cell lines and collected RNA from tumor cells treated differently." (PMID 39247811, 2024). "Both PUS1 and TRUB2 were aberrantly expressed in 79% of the tumor types." (PMID 39162904, 2024). "In conclusion, high expression of PUS1 is correlated with the malignancy of NSCLC and may promote tumor development." (PMID 37925171, 2023). "We initially calculated the univariate and multivariate analysis of overall survival (OS) rate, including the expression of genes belonging to the PUS family (PUS1, PUS3, PUS7, PUS10, PUS7L, PUSL1), patients’ age, gender, race and Tumor Node Metastasis (TNM)-stage, and set grade as co-variate." (PMID 37315299, 2023).
tumor (continued). "A positive correlation was found between the PUS1 expression TNBC status (P= 0.020) and tumor grade (P <0.0001), but not with age (P= 0.736), tumor size (P= 0.608), lymph node (P= 0.742), ER (P= 0.162), PR (P= 0.901), HER (P= 0.608) or tumor stage (P= 0.411)." (PMID 36457503, 2022). "In the GSE59612 dataset, the expression of PUS1, PUS7, RPUSD1 and DKC1 were significantly increased in the tumor core tissues relative to tumor marginal tissues and paracancerous tissues; and the expression of TRUB1 was decreased from paracancerous tissue to tumor core tissue." (PMID 35118063, 2021).
cancer (11 papers, 2018 to 2026). A tumor composed of atypical neoplastic, often pleomorphic cells that invade other tissues. "Certain members, including DKC1, PUS1, and PUS7, have been implicated in oncogenic processes such as cancer stemness, metabolic reprogramming, and immune regulation across various malignancies." (PMID 41496500, 2026). "Our result indicated that PUS1 expressed significantly higher in cancer tissues than adjacent liver tissues of HCC patients, in line with the results of the patient data analysis of THE HUMAN PROTEIN ATLAS database." (PMID 40171259, 2025). "PUS1 expression knockdown significantly affects a range of cancer-related biological processes, such as the regulation of cell proliferation and cell migration, mitochondrial autophagy, and PI3K/Akt signaling." (PMID 39162904, 2024). "In fact, up-regulation of PUS1 enhances RCC cancer cell viability, migration, invasion and colony formation ability, while decreased PUS1 expression exerts the opposite effects on RCC cells." (PMID 38476632, 2024). "Consistently, by overexpression of PUS1 and knockdown of PUS1 in RCC cells in vitro, we showed that PUS1 expression was significantly associated with cancer cell malignancy, including cell viability, migration, invasion and colony formation ability." (PMID 37315299, 2023). "Cancer cells are significantly inhibited in their ability to proliferate, form colonies, and invade when PUS1 is inhibited." (PMID 36457503, 2022). "A Gene Ontology (GO) analysis was conducted to investigate the functions of downstream genes of PUS1 and the biological processes related to a series of cancer related signature such as cell proliferation and cell migration." (PMID 36457503, 2022). "RNA sequencing data revealed the PUS1 knockdown significantly affects a series of cancer related biological process such as regulation of cell proliferation and cell migration, as well as KEGG pathways including Mitophagy and PI3K-Akt signaling." (PMID 36457503, 2022). "We found that PUS1 regulated many cancer-related biological process including cell proliferation and cell migration." (PMID 36457503, 2022). "Moreover, results based on the immunohistochemically staining of PUS1 in cancer and normal tissues of HCC patients in THE HUMAN PROTEIN ATLAS database showed that PUS1 was highly expressed in HCC patients." (PMID 40171259, 2025). "Recent work has found PUS1 to be upregulated in various cancers including HCC, and may contribute to oncogenesis in HCC." (PMID 39337628, 2024). "In addition, the upregulated PUS1 expression results in the elevated RCC cancer cell viability, migration, invasion and colony formation ability, whereas the decreased PUS1 expression exerts the opposite effects on RCC cells." (PMID 37315299, 2023). "Moreover, according to in vitro RNA sequencing analysis data, up-regulation of PUS1 expression affected a range of cancer related pathways." (PMID 37315299, 2023). "As expected, both KEGG pathway analysis and GO bioinformatic analysis indicate that the altered expression of PUS1 is related to multiple pathways, including cancer pathways and cell function progressions, such as cell proliferation, cell growth, cell movement, cell death and cell differentiation." (PMID 37315299, 2023). "In vitro, downregulation of PUS1 affects a variety of cancer related pathways." (PMID 36457503, 2022). "In addition, we identified several novel oncogenic enzymes with up-regulation in multiple cancer types, including PUS1, a tRNA pseudoridylate synthase, and TRMT1 and TRMT6, the tRNA methyltransferases." (PMID 30588513, 2018). "PUS7, PUS1, and DKC1 are significantly up-regulated in cancer tissue at both mRNA and protein levels." (PMID 37925171, 2023). "We also noticed that PUS1 affect many crucial pathways including Mitophagy, PI3K-Akt signaling pathways which were frequently deregulated in cancers." (PMID 36457503, 2022).
cancer (continued). "Despite the latest research reported that PUS1 promotes HCC through mRNA pseudouridylation to enhance the translation of oncogenic mRNAs, the biological role and mechanism of PUS1 remain poorly understood, especially in human cancer." (PMID 40171259, 2025). "In conclusion, Ψ has emerged as a potential player in cancer processes and PUS1 may be a potential therapy target and novel biomarker in NSCLC." (PMID 37925171, 2023). "It has not been reported in previous study that PUS1 impacted the cell phenotype of cancer cells." (PMID 36457503, 2022).
myopathy (6 papers, 2011 to 2023). A disease of the muscle in which the muscle fibers do not function properly. "Myopathy, lactic acidosis, sideroblastic anemia (MLASA) syndrome is a rare autosomal recessive disease caused by recessive mutations in PUS1 encoding the pseudouridine synthase 1 enzyme." (PMID 29980628, 2018).